TF (transferrin)
Diseases named in the same sentence as TF in open-access papers (continued):
Sharing a sentence is not in itself a finding about the gene and the disease.
iron overload (continued). "Maintaining a regular hemoglobin level can be achieved by using regular ESA doses combined with intravenous iron doses adapted to S-ferritin (SF) and transferrin saturation (TSAT) thresholds that are lower than those used in routine practice; this contributes to a reduced risk of iron overload." (PMID 33461526, 2021). "This may be due to the fact that elevations in transferrin saturation typically precede a rise in serum ferritin in patients with iron overload as reported by Lam." (PMID 34795732, 2021). "High transferrin saturation as a sign of iron overload and a low SHP concentration as a sign of redox imbalance in obese patients might reflect underlying mechanisms that could in part explain the associations of iron overload and obesity with CRA." (PMID 34439443, 2021). "The exercise-related iron overload is mostly originated from the iron-stocking proteins ferritin and transferrin in the bloodstream or in specific organs, such as the spleen and liver, and also in heme-iron forms from erythrocytes (hemolysis) and contractile muscle fibers (rhabdomyolysis)." (PMID 33809996, 2021). "Indeed, it was reported that the TFR for importing iron into hepatocytes by receptor-mediated endocytosis of transferrin-iron complex plays a critical role in hepatic iron overload in patients with ALD." (PMID 34199599, 2021). "Finally, a slow and progressive increase in ferritin over time indicates an ongoing iron overload, and an elevated transferrin saturation can usually confirm this." (PMID 34067164, 2021). "Another factor as iron overload, evidenced by higher serum ferritin and transferrin saturation, could also have contributed to the high mortality rate in the Tx group." (PMID 31978190, 2020). "In conditions of systemic iron overload, which cause transferrin saturation to rise above 60%, non-transferrin-bound iron (NTBI) accumulates." (PMID 30609678, 2019). "The difficulty in the interpretation of increased ferritin is related to the multiple causes that can lead to its increase, initially identified as marker of iron overload, following the increase of transferrin saturation, and also in the presence of severe hepatic necrosis." (PMID 27077854, 2016). "Therefore, a transferrin saturation cutoff value > 45% has been suggested as a good predictor of iron overload." (PMID 27007895, 2016). "An accurate diagnosis requires the detection of increases in the main biochemical markers of iron overload, i.e., serum ferritin and the transferrin saturation index; the appearance of clinical manifestations should be noted, and mutations should be identified by genetic testing." (PMID 26197432, 2015). "For this reason, transferrin saturation is used as a complement in the iron overload diagnosis." (PMID 26451235, 2015). "As expected, as compared with patients with compound heterozygosity, those with the homozygous C282Y/C282Y genotype showed significantly higher ferritin concentration and transferrin saturation values, and about half of the homozygous patients showed severe iron overload." (PMID 25822977, 2015). "In contrast, elevated transferrin saturation and splenic iron overload are variably present." (PMID 20691492, 2010). "The answer is complex, but in this article we explore the pros and cons of screening for HH and the different views regarding whether it should be phenotypic (screening for iron overload by serum ferritin and/or transferrin saturation) or genotypic (testing for HFE p.Cys282Tyr)." (PMID 39202328, 2024). "Firstly, several parameters determining functional and storage iron pool, including TIBC and serum levels of transferrin and ferritin, confirmed that the degree of iron overload may depend on the treatment modalities and is dominant in pediatric patients post-HCT." (PMID 36831385, 2023).
iron overload (continued). "Annual monitoring with measurements of serum ferritin and transferrin saturation of subjects with p.Cys282Tyr/p.His63Asp compound heterozygosity or p.His63Asp homozygosity and normal iron indices is acceptable recognizing the probability of developing significant iron overload is low." (PMID 37067673, 2023). "A recent report indicates that TF can quickly enter the bloodstream from the brain through the BBB, suggesting that TF and TFR may exert dual effects on iron overload, i.e., they may not only cause iron overload but may also promote iron clearance in the brain when iron overload occurs." (PMID 35481263, 2022). "Investigations of TF, FTL, PCBP1 and VDAC3 and their different specificities in terms of their roles in iron metabolism, independent of lipid-lowering treatment actions, may also be of high interest in the treatment of iron overload and deficiency." (PMID 35181730, 2022). "Thus, the observed association of transferrin saturation with CRA is likely a sign of iron overload that is not caused by excessive dietary haem consumption but by other reasons." (PMID 34439443, 2021). "Furthermore, in iron overload patients with increased ferritin (women ≥ 150 to 200 ng/mL and men ≥ 200 to 300 ng/mL) and transferrin saturation ≥ 45%, genetic testing for hereditary haemochromatosis is warranted as erythrocytosis sometimes, yet rarely, appears in haemochromatosis patients." (PMID 34013406, 2021). "In other words, if NTBI is considered in a continuum with TBI above the saturation point of Tf, it is evident that plasma iron above the saturation point of Tf (NTBI) does not associate with ferritin (and therefore with iron overload), whereas the plasma iron on transferrin does." (PMID 27344508, 2016). "Although low total adiponectin levels have been reported in patients with non-alcoholic fatty liver disease and inversely associated with serum ferritin and transferrin, total adiponectin does not appear to correspond to insulin resistance promoted by iron overload in dolphins." (PMID 24065958, 2013). "Iron overload consistently increased serum iron and decreased TIBC and TF% compared to the control group, with these serum iron-related indices significantly returning to normal levels following theaflavins administration (p < 0.01)." (PMID 40384858, 2025). "Exceeding the iron-binding capacity of transferrin results in the formation of non-transferrin-bound iron (NTBI), which can penetrate cells and lead to iron overload." (PMID 40286136, 2025). "The transferrin levels in both FID and CRA patients are significantly lower compared to the AID, IDA, normal iron status, iron overload, and control." (PMID 36555993, 2022). "Serum non-transferrin bound iron (NTBI) levels appeared modestly elevated in the dietary and genetic iron overload models and seemed to decrease in Hjv-/- mice following IDD intake." (PMID 36066082, 2022). "The normal range of plasma transferrin saturation (TSAT) is usually 20–40% and rarely exceeds 60%, except in systemic iron overload conditions such as in hereditary haemochromatosis." (PMID 32711469, 2020). "We considered transferrin saturation index (TSI) as the most specific and sensitive parameter in identifying iron overload as it showed a significant statistical difference between responder group (27.5%) and NR (34.5%) group with p-value <0.001." (PMID 29201799, 2017). "The recent description that serum transferrin is a limiting resource for the size of the MHC class I dependent lymphocyte pool, and that the lowest transferrin levels are observed in males, may help to explain the increased susceptibility of males to iron overload." (PMID 16509978, 2006). "Iron overload in renal tissue occurred during septic inflammation and contributed to renal damage more than the systemic increase in which the serum transferrin level was not affected." (PMID 39949667, 2025).
iron overload (continued). "Serum ferritin concentration and transferrin saturation are commonly employed to estimate body iron but are non-specific to iron overload." (PMID 39262540, 2024). "Of the remaining 4 participants, 3 had abnormal serum ferritin result and 1 also had abnormal transferrin saturation level, although none met laboratory criteria for iron overload." (PMID 37870835, 2023). "While generalized population screening for iron overload is not recommended, patients with suspected iron overload are identified by elevated serum ferritin and transferrin saturation > 45% followed by genetic testing for HFE p.Cys282Tyr and p.His63Asp." (PMID 37067673, 2023). "The classical phenotype is characterised by raised ferritin, normal transferrin and iron overload in macrophages, and in the non-classical phenotype ferritin and transferrin are both raised and iron overload affects the liver as well as macrophages." (PMID 37029208, 2023). "The degree of iron overload evaluated by measuring serum ferritin and transferrin saturation are inexpensive and helpful but are non-specific." (PMID 35624729, 2022). "Whilst a normal transferrin saturation usually excludes pathologically increased iron absorption, it does not necessarily exclude the presence of an iron overload." (PMID 34067164, 2021). "While administration of transferrin yielded promising results in various clinical conditions such as atransferrinemia and iron overload or in animal models of β-thalassemia, it was never tested in the context of liver disease." (PMID 33593348, 2021). "In the case of iron overload, the iron-binding ability of transferrin is highly exceeded, and thus non-transferrin-bound iron (NTBI) appears in the blood." (PMID 34204310, 2021). "The mean serum ferritin and transferrin saturation values were higher among subjects with iron overload than subjects without iron overload but the observed difference was not significant (p = 0.109, 0.236 respectively)." (PMID 34795732, 2021). "NTBI can be observed in the blood of patients with iron overload conditions when transferrin is saturated, although its presence has also been detected at not fully saturated transferrin levels." (PMID 34831062, 2021). "Transferrin saturation is a useful parameter for the distinction of the presence or absence of an iron overload upon hyperferritinemia." (PMID 34067164, 2021). "In general, with advanced states of iron overload, transferrin will be saturated and iron will be free in a non-transferrin bound form." (PMID 33003498, 2020). "Compared to Pi*Z non-carriers, Pi*ZZ individuals had elevated serum iron, transferrin saturation, and ferritin levels, but relevant iron overload was rare." (PMID 31717526, 2019). "A possible reason for not detecting an increase in C282Y homozygotes in the OA group is that subjects in our study were not primarily selected by iron overload and few suffered from elevated serum ferritin and transferrin saturation levels." (PMID 30427934, 2018). "In our study, apart from sTfR (itself a marker of cellular iron demand rather than iron overload), values for the concentration of plasma ferritin, transferrin, and transferrin saturation all remained altered at 8 and 43 days post-iron infusion." (PMID 27418684, 2016). "Although symptoms of obvious iron overload were absent in the father, his serum iron concentration of 33.44 μmol/L was slightly elevated and the 198 mg/dL transferrin value was close to the lower limit of the normal range." (PMID 25262004, 2014). "The presence of excessive ferritin level in absence of high-transferrin saturation helps differentiate secondary iron overload from hemochromatosis where transferrin saturation is typically high." (PMID 24024049, 2013). "We have already demonstrated that during iron overload there is an increased expression of ferritin, although not accompanied by an up-regulation of transferrin, most likely due the already high levels of constitutive expression in the liver." (PMID 21501491, 2011).
iron overload (continued). "A high ferritin value and a normal transferrin saturation in an otherwise healthy young adult virtually excludes iron overload." (PMID 21936912, 2011). "When transferrin iron binding capacity is exceeded and NTBI is detectable in circulation, iron trafficking is dysregulated and results in the clinical manifestations of iron overload." (PMID 20631898, 2010). "This review is focused on the forms of inherited hyperferritinemia with or without iron overload presenting with normal transferrin saturation, as well as a step-by-step approach to distinguish these forms to the acquired forms, common and rare, of isolated hyperferritinemia." (PMID 36768886, 2023). "Increased serum ferritin might be found in patients with or without iron overload and with or without increased transferrin saturation (TSAT) and often requires an extensive diagnostic work-up." (PMID 36768886, 2023). "Also, a higher but not significantly different mean serum transferrin and transferrin saturation in subjects with iron overload than those without iron overload." (PMID 34795732, 2021). "A growing body of knowledge exists on the pathophysiology of iron-overload–induced tissutal toxicity: once transferrin is saturated, non-transferrin-bound iron becomes detectable, and—because of iron's ability to transfer electrons—this results in oxidative stress." (PMID 34900873, 2021). "In systemic iron overload, elevated circulating levels of transferrin-bound (TBI) and non-transferrin-bound iron (NTBI) are filtered to the renal proximal tubules, where they may cause injury." (PMID 30806852, 2019). "The transferrin saturation phenotype screening of two Native American populations in Canada (1407 "Native Americans," 310 Inuit) revealed no subject with evidence of iron overload." (PMID 16533407, 2006). "Furthermore, the presence of NTBI does not always correspond directly to transferrin saturation levels and may be affected by conditions unrelated to iron overload, such as infection or inflammation." (PMID 40650208, 2025). "It should be noted that low serum transferrin due to the impaired synthetic function of the liver upon chronic liver disease may be misleading in the diagnostic workup, as this potentially results in an elevated transferrin saturation, even in the absence of an iron overload." (PMID 34067164, 2021). "It should also be noted that transferrin saturation predicts hepatic iron overload (HIO) better in C282Y homozygotes than in non-C282Y homozygotes and non-HFE iron overload (type 2–4 HH)." (PMID 34067164, 2021). "Transferrin seems to be a useful biomarker too, but it is not easily reliable in allo-HSCT, because patients are always hyper-transfused and often present an iron overload." (PMID 33488571, 2020). "While most iron circulates in blood as transferrin-bound iron, non-transferrin-bound iron (NTBI) also becomes elevated and contributes to toxicity in the setting of iron overload." (PMID 18254965, 2008). "Transferrin saturation has high biological variability and low sensitivity to detect HFE-related hemochromatosis and a retrospective review of outpatient referrals for elevated serum ferritin found 64% of patients with a serum ferritin threshold over 1000 μg/L did not have iron overload on biopsy." (PMID 37067673, 2023).
breast carcinoma (134 papers, 1983 to 2026). "We have previously demonstrated in breast cancer cells that increased TF expression is associated with enhanced cancer cell migration." (PMID 25886038, 2015). "We did not observe statistical enrichment (random n = 10,000) of the breast cancer risk loci in DNase hypersensitivity, ChromHMM enhancer, Segway enhancer data, or TF union data for GM12878." (PMID 26422229, 2015). "EMT is believed to play an important role in intravasation and the release of CTCs, and the expression of EMT-inducing TF gene transcripts in breast cancer has been associated with poor prognosis." (PMID 24972610, 2014). "It has been postulated that abemaciclib also increases the risk of thrombosis in breast cancer patients, which may be due to TF release." (PMID 38986222, 2024). "In this study, the serum levels of transferrin and lipocalin 2 were evaluated and compared between patients with breast cancer and healthy women." (PMID 40450119, 2025). "Along the same line, transferrin (Tf)-conjugated DOX-loaded CQDs were developed to act against breast cancer cells." (PMID 40075725, 2025). "On this basis, we discussed the existing methods and drug resistance of FOX TF-based breast cancer treatment." (PMID 40003882, 2025). "We believe that more studies are needed to prove the more common influence of FOX TF on drug resistance to breast cancer." (PMID 40003882, 2025). "As we just discussed, FOX TF itself is diverse, and it has different or even opposite roles in different types of breast cancer." (PMID 40003882, 2025). "Nevertheless, we believe that FOX TF still has considerable potential in the treatment of breast cancer." (PMID 40003882, 2025). "The aim of this study was to investigate the serum levels of transferrin and lipocalin 2 in Syrian breast cancer patients, and compare them with those in a control group and their correlation with the tumor state and characteristics." (PMID 40450119, 2025). "In this study we evaluated the serum levels of transferrin and lipocalin 2 in Syrian breast cancer patients and compared them with those in a control group, and we also studied the correlation of their levels with the tumor status in patients." (PMID 40450119, 2025). "Highly luminescent carbon quantum dots (CQDs) were synthesized via the carbonization of citric acid and modified with transferrin (TF) to improve water solubility and facilitate the targeted delivery of doxorubicin (Dox) to breast cancer cells." (PMID 38730959, 2024). "The flow cytometric outcomes determined that the transferrin-mediated SLNs nanocurcumin has possibly elevated the anticancer activity of curcumin in breast cancer cell lines in in vitro studies compared to the standard group." (PMID 39844869, 2024). "For instance, researchers aimed to develop targeted drug delivery systems, particularly for breast cancer therapy, by employing transferrin-conjugated CQDs (TF-CQDs) loaded with doxorubicin." (PMID 39124888, 2024). "The anticancer activity was evaluated against breast cancer cell lines by stimulation of apoptosis using transferrin-mediated solid lipid nanoparticles (SLNs) of curcumin." (PMID 39844869, 2024). "For instance, a study described the development and characterization of SLNs conjugated with transferrin for the delivery of tamoxifen citrate, a widely used therapeutic agent for breast cancer therapy." (PMID 39124888, 2024). "It is similar to a previous study within breast cancer cells, in which ERK1/2 kinase activity was measured in nuclear extracts and shown to be upregulated in MDA-MB-231 breast cancer cells with higher expression of TF mRNA." (PMID 37940761, 2024). "The analytic sample included 2,494 incident breast cancer cases with information on tumor size and iron biomarkers, including serum iron (mcg/dL), ferritin (mcg/dL), and percent transferrin saturation, measured in serum collected at baseline." (PMID 38112642, 2024).